TMUB1 (transmembrane and ubiquitin like domain containing 1)
Diseases named in the same sentence as TMUB1 in open-access papers (continued):
Sharing a sentence is not in itself a finding about the gene and the disease.
glioma (continued). "The knockdown of TMUB1 not only confirmed its influence on glioma cell growth but also provides valuable insights into the potential therapeutic strategies targeting TMUB1 for glioma treatment." (PMID 38148953, 2023). "Collectively, the results from both datasets emphasize the clinical relevance of TMUB1 as a prognostic marker in glioma." (PMID 38148953, 2023). "Our results revealed a significant upregulation of TMUB1 expression in glioma tissues, highlighting its potential role in glioma development." (PMID 38148953, 2023). "This study is aimed at investigating the functional significance and clinical relevance of TMUB1 in glioma." (PMID 38148953, 2023). "TMUB1 emerges as a novel and clinically relevant prognostic biomarker for gliomas." (PMID 38148953, 2023). "In this paper, we delve into the pivotal role of TMUB1 in glioma pathogenesis." (PMID 38148953, 2023). "Cellular experiments demonstrated that TMUB1 silencing suppressed the growth of glioma cells." (PMID 38148953, 2023). "Additionally, we performed TMUB1 knockdown in U87 and LN-229 human glioma cell lines, and cellular growth was assessed through the 3-(4,5-dimethylthiazol-2-yl)-2,5-diphenyl-2H-tetrazolium bromide (MTT) assay." (PMID 38148953, 2023). "However, the specific mechanisms through which TMUB1 promotes glioma progression warrant further investigation." (PMID 38148953, 2023). "Furthermore, our functional experiments reveal that TMUB1 knockdown significantly inhibits glioma cell growth, offering a mechanistic understanding of its oncogenic role." (PMID 38148953, 2023). "Targeting TMUB1 holds promise as a potential strategy for glioma treatment." (PMID 38148953, 2023). "This mechanistic insight underscores the potential of TMUB1 as a therapeutic target in glioma." (PMID 38148953, 2023). "Moreover, patients with higher TMUB1 levels in glioma tissues exhibited worse prognosis in both TCGA cohort and our retrospective cohort, underscoring its prognostic significance in gliomas." (PMID 38148953, 2023). "Notably, TMUB1 expression was significantly higher in glioma tissues without 1p/19q codeletion, suggesting a potential association between TMUB1 levels and molecular subtypes of glioma." (PMID 38148953, 2023). "Besides TMUB1, the prognostic significance of other variables in our cohort was also evaluated to provide a comprehensive understanding of the prognostic significance of various factors in glioma patients." (PMID 38148953, 2023). "Furthermore, we conducted an analysis of the correlations between clinical characteristics and TMUB1 mRNA levels in the cohort of glioma patients from our hospital (Suining Central Hospital, SCH), aiming to further elucidate the potential associations between these factors and TMUB1 expression." (PMID 38148953, 2023). "Transmembrane and ubiquitin-like domain-containing 1 (TMUB1) is a recently discovered protein in the ubiquitin-like domain family, yet its involvement in glioma remains poorly understood." (PMID 38148953, 2023). "Subsequently, we examined TMUB1 expression in glioma tissues with and without 1p/19q codeletion." (PMID 38148953, 2023). "Furthermore, we explored the relationship between TMUB1 expression and the WHO grade of glioma." (PMID 38148953, 2023). "Although the tumor-related role of TMUB1 in other malignancies was slightly mentioned in lung cancer and pancreatic cancer, direct evidence was lacking, especially whether TMUB1 contributes to glioma development and progression is still unclear." (PMID 38148953, 2023).
intestinal cancer (1 paper, 2023). "The expression levels of TMUB1 in intestinal cancer cell lines as well as in 10 intestinal cancer tissues were verified by qPCR experiments." (PMID 38025742, 2023).
tumor (9 papers, 2022 to 2025). "TMUB1 protein levels correlate with PD-L1 expression in human tumor tissue, with high expression being associated with poor patient survival rates." (PMID 36376293, 2022). "In addition, the association of TMUB1 in tumor microenvironment and immune cell infiltration was analyzed." (PMID 38025742, 2023). "Recent studies indicate that TMUB1 greatly facilitates antitumor immunity and inhibits tumor growth in mice, and it can serve as a potential candidate target to improve the prognosis of cancer‐immune patients." (PMID 37249279, 2023). "Patients with tumors larger than 5.0 cm exhibited a higher prevalence of high TMUB1 expression compared to those with smaller tumors, suggesting a positive correlation between larger tumor size and increased TMUB1 expression." (PMID 38148953, 2023). "Considering that both TCGA cohort and our SCH cohort indicate that tumor size and WHO grade are significantly associated with TMUB1 expression, we next conducted survival analyses to further illustrate its clinical relevance." (PMID 38148953, 2023). "Elevated TMUB1 expression is linked to unfavorable clinical features such as higher WHO grades, advanced age, larger tumor size, and wild-type IDH1/2 status." (PMID 38148953, 2023). "The possible molecular mechanism of TMUB1 interaction with tumorigenesis and tumor immunity was comprehensively analyzed and discussed." (PMID 38025742, 2023). "The overexpression of TMUB1 in tumor cell lines was shown to strongly reduce proliferation by arresting the cell cycle in G0/G1." (PMID 35928927, 2022). "In line with the mechanistic findings, the IHC and flow cytometry analyses of the tumor tissues revealed that Tmub1-knockdown significantly reduced the PD-L1 levels in EO771 tumor cells." (PMID 36376293, 2022). "We detected a significant difference between TMUB1 overexpression and T stage (P < 0.001), pathologic stage, and residual tumor when the Kruskal-Wallis rank sum test was used." (PMID 35928927, 2022). "Analysis using the Wilcoxon rank sum test revealed that the expression level of TMUB1 in 619 tumor tissues was higher than that in 51 normal tissues (P < 0.001)." (PMID 35928927, 2022). "The high TMUB1 expression was significantly correlated with T stage (P = 0.046) and residual tumor (P = 0.001) using chi-square test or Fisher's exact test." (PMID 35928927, 2022). "A synthetic peptide engineered to compete with TMUB1 significantly promotes antitumor immunity and suppresses tumor growth in mice." (PMID 36376293, 2022). "To this end, we have developed a peptide targeting TMUB1 and have achieved significant therapeutic results in tumor-bearing mice." (PMID 36376293, 2022). "Here, we identify transmembrane and ubiquitin-like domain-containing protein 1 (TMUB1) as a modulator of PD-L1 post-translational modifications in tumor cells." (PMID 36376293, 2022). "Future investigations into the molecular pathways influenced by TMUB1 and its interactions within the tumor microenvironment may offer novel therapeutic strategies for this challenging cancer." (PMID 38148953, 2023). "Likewise, using the Wilcoxon signed rank test, we observed that the expression of TMUB1 was significantly higher in 50 tumor tissues than that in the 50 paired normal tissues in the TCGA cohort (P < 0.001)." (PMID 35928927, 2022). "However, reduced EO771 and 4T1 tumor growth was observed in the Tmub1-knockdown group in the immunocompetent C57LB/6 and Balb/c mice." (PMID 36376293, 2022). "Furthermore, the knockdown of Tmub1 also had a significant effect on the tumor immune microenvironment." (PMID 36376293, 2022).
tumor (continued). "Bioinformatic analysis of high throughput RNA-sequencing data from TCGA demonstrated that the TMUB1 overexpression in CRC was associated with T stage, residual tumor, and poor prognosis, suggesting that TMUB1 may serve as a prognostic marker in CRC." (PMID 35928927, 2022). "Most importantly, the levels of total and activated CD8+ cytotoxic T cells (GzmB+) that infiltrated the tumor microenvironment increased, while the proportion of exhausted CD8+ T cells decreased, indicating that the deficiency of Tmub1 maintains high cytotoxic T lymphocyte activity." (PMID 36376293, 2022). "Moreover, we show that a peptide targeting the interaction between TMUB1 and PD-L1 can promote anti-tumor immune responses in mouse models." (PMID 36376293, 2022). "The high expression of TMUB1 in CRC was associated with T stage, neotype, and residual tumor." (PMID 35928927, 2022). "Interestingly, TMUB1 knockdown attenuated the tumor cell-induced immune suppression, leading to an increased T cell-mediated death of cancer cells." (PMID 36376293, 2022). "In addition, TMUB1 mediates immune cell infiltration in the tumor microenvironment." (PMID 38025742, 2023). "In conclusion, TMUB1 is a potential candidate target that could be utilized to improve patient outcomes in cancer immune check blockade therapy owing to its influence on the PD-L1 level in the tumor microenvironment." (PMID 36376293, 2022). "Moreover, TMUB1 enhances PD-L1 N-glycosylation and stability by recruiting STT3A, thereby promoting PD-L1 maturation and tumor immune evasion." (PMID 36376293, 2022).
cancer (7 papers, 2022 to 2024). A tumor composed of atypical neoplastic, often pleomorphic cells that invade other tissues. "This aligns with studies in other cancers where TMUB1 has been implicated in cell proliferation, apoptosis, and invasion." (PMID 38148953, 2023). "TMUB1 deficiency increases cancer cell sensitivity to T cell-mediated cytotoxicity and enhances antitumor immune response in mice." (PMID 36376293, 2022). "This aligns with prior studies where TMUB1 overexpression has been correlated with malignancy in other cancer types, suggesting a general oncogenic role for TMUB1." (PMID 38148953, 2023). "In summary, our study revealed two regulators of PD-L1, namely, TMUB1 and HUWE1, and connected TMUB1 with immune evasion by cancer cells." (PMID 36376293, 2022). "Accumulating evidence suggests that, in addition to being involved in cell proliferation, TMUB1 is a critical regulator of apoptosis, genomic stability, and cancer development." (PMID 36376293, 2022). "Collectively, these results suggested that TMUB1 could increase the PD-L1 levels in cancer cells and promote immune evasion." (PMID 36376293, 2022). "Collectively, our study demonstrates that TMUB1 regulates the cellular abundance of PD-L1 to promote cancer cell evasion and may represent a potential target for immunotherapy." (PMID 36376293, 2022). "Hence, the correlation between immune cells and TMUB1 suggested that TMUB1 plays a complex role in regulating cancer immunity because of the various roles it plays in immune cells." (PMID 35928927, 2022). "TMUB1 was found to bind non-glycosylated PD-L1 in the endoplasmic reticulum and recruit STT3A to promote glycosylation of PD-L1, resulting in its protection from being ubiquitinated upon HUWE1 binding and ultimately increasing the levels of PD-L1 in different cancer types." (PMID 36376293, 2022).
gastrointestinal tumors (1 paper, 2023). "Similarly, TMUB1 was found to be significantly overexpressed in gastrointestinal tumors in paired samples." (PMID 38025742, 2023).
infection (1 paper, 2022). The state of being infected such as from the introduction of a foreign agent such as serum, vaccine, antigenic substance or organism. "The stability ranking at different developmental stages associated with infection of PWN was as the following: TER > RPL7 > RPS5 > Zdhhc15 > EF1-γ > RPL18 > Tmub1 > SNX6 > ATPase > TFAM > α-TUB > EIF > TPI > COX7." (PMID 35547586, 2022).
TMUB1 also shares sentences with these, for which no sentence is quoted: adenocarcinoma (1 paper); colon adenocarcinoma (1); epilepsy (1); invasive breast carcinoma (1); lung adenocarcinoma (1); lung carcinoma (1); oligoastrocytoma (1); oligodendroglioma (1); pancreatic adenocarcinoma (1); pancreatic cancer (1); rectum adenocarcinoma (1); resistant hypertension (1); stomach adenocarcinoma (1).